COL13A1 (collagen type XIII alpha 1 chain)
Description:
Involved in cell-matrix and cell-cell adhesion interactions that are required for normal development. May participate in the linkage between muscle fiber and basement membrane. May play a role in endochondral ossification of bone and branching morphogenesis of lung. Binds heparin. At neuromuscular junctions, may play a role in acetylcholine receptor clustering.
Synonyms: CMS19; COLXIIIA1
Tractability: Antibody: UniProt places it where antibodies can reach, with high confidence; its Gene Ontology location is reachable by antibodies, with high confidence; UniProt predicts a signal peptide or a membrane-spanning region.
Gene: Protein-coding gene on chromosome 10 (69,801,880 to 69,964,275, forward strand). Ensembl gene ENSG00000197467.
Subcellular location: Cell membrane; Postsynaptic cell membrane
Pathways (Reactome):
Extracellular matrix organization: Collagen biosynthesis and modifying enzymes; Collagen chain trimerization; Collagen degradation; Integrin cell surface interactions
Gene Ontology:
Molecular function: heparin binding; protein binding; extracellular matrix structural constituent conferring tensile strength
Biological process: cell-cell adhesion; cell-matrix adhesion; endochondral ossification; extracellular matrix organization; morphogenesis of a branching structure
Cellular component: extracellular matrix; plasma membrane; postsynaptic membrane; basement membrane; collagen type XIII trimer; endoplasmic reticulum lumen; extracellular region
Genetic constraint (gnomAD): Loss-of-function variants: 78 observed, 106.34 expected, observed/expected ratio (o/e) 0.73, 90% interval 0.61 to 0.89. The synonymous counts are far from expectation, so gnomAD's model fits this gene poorly and the ratio says little. Missense variants: 825 observed, 814.64 expected, observed/expected ratio (o/e) 1.01, 90% interval 0.96 to 1.07. Synonymous variants: 371 observed, 301.28 expected, observed/expected ratio (o/e) 1.23, 90% interval 1.13 to 1.34.
Homologues: Orthologues: chimpanzee COL13A1 (95% identical), macaque COL13A1 (94% identical), pig COL13A1 (92% identical), dog COL13A1 (89% identical), guinea pig COL13A1 (87% identical), mouse Col13a1 (87% identical), rat Col13a1 (87% identical), tropical clawed frog col13a1 (58% identical), Caenorhabditis elegans col-99 (30% identical). Paralogues in human: COL7A1 (48% identical), COL4A5 (44% identical), COL4A1 (43% identical), COL4A6 (42% identical), COL4A3 (42% identical), COL4A2 (42% identical), COL5A1 (38% identical), COL2A1 (38% identical), COL11A1 (38% identical), COL11A2 (37% identical), COL4A4 (37% identical), COL1A1 (36% identical), and 25 more.